MMP2 (matrix metallopeptidase 2)
Diseases named in the same sentence as MMP2 in open-access papers (continued):
Sharing a sentence is not in itself a finding about the gene and the disease.
nasopharyngeal carcinoma (44 papers, 2013 to 2025). A carcinoma arising from the nasopharyngeal epithelium. "TIMP-2 upregulation was linked to metastasis via MMP-2 inactivation in nasopharyngeal carcinoma." (PMID 32560557, 2020). "For MMP2-1306 C>T polymorphism, significant associations were observed under three genetic models both in overall comparison and in a hospital-based subgroup, and in oral cavity cancer and nasopharyngeal cancer under dominant model as well." (PMID 23637955, 2013). "Research has demonstrated that dihydromyricetin impedes cell migration and MMP-2 expression in human nasopharyngeal carcinoma, with this action mediated through the ERK1/2 signaling pathway." (PMID 38374934, 2024). "MMP2 knockdown significantly inhibited the colony formation and migration of nasopharyngeal cancer cells." (PMID 36677584, 2023). "An MMP2-silencing experiment demonstrated that short hairpin (sh) RNA-transfected nasopharyngeal carcinoma CNE-1 cells showed inhibited cell colony formation compared to the control cells." (PMID 36677584, 2023). "MMP-2 knockdown drastically reduced nasopharyngeal cancer cell growth and migration, while overexpression of MMP-2 prevented the inhibitory impact of miR-299-3p overexpression on nasopharyngeal cancer cells migration and propagation." (PMID 36059797, 2022). "Overexpression of MMP-2 substantially reduced the miR-299-3p inhibitory impact on nasopharyngeal cancer cell migration and colony formation." (PMID 36059797, 2022). "Using miR-299-3p mimics, nasopharyngeal cancer cells showed substantial decreases in MMP-2 mRNA and protein expression levels." (PMID 36059797, 2022). "The colony formation test was performed to investigate the impact of MMP-2 knockdown on nasopharyngeal cancer cell growth." (PMID 36059797, 2022). "The miR-299-3p acts as a tumor suppressor gene to suppress the growth and spread of nasopharyngeal cancer by regulating MMP-2 expression." (PMID 36059797, 2022). "Nasopharyngeal cancer tissues had an MMP-2 activity level much greater than normal nasopharyngeal tissues, and the clinical stage of nasopharyngeal carcinoma was strongly correlated with MMPs activity." (PMID 36059797, 2022). "Overexpression of ATF1 in nasopharyngeal carcinoma was positively correlated with the expression of MMP2." (PMID 35397606, 2022). "High MMP-2 expression has been associated with poor prognosis and the induction of EMT in nasopharyngeal carcinoma." (PMID 34502112, 2021). "In nasopharyngeal cancer, FBLN2 inhibits the metastatic properties via downregulation of vascular endothelial growth factor (VEGF) and matrix metalloproteinase 2 (MMP2), one of the ECM associated enzymes." (PMID 34769264, 2021). "In Epstein-Barr virus (EBV) associated nasopharyngeal carcinoma, latent membrane protein 1 (LMP1) is the viral oncogene that promotes invasion and metastasis through effects on MMP-2/9." (PMID 34790909, 2021). "MMP14 not only promotes cell migration, invasion, and angiogenesis in nasopharyngeal carcinoma and pituitary adenomas but also promotes the secretion of pro-MMP2 and pro-MMP9." (PMID 30886783, 2019). "The findings of this study demonstrated that nasopharyngeal cancer cell proliferation and migration could be inhibited by knocking down MMP-2 expression." (PMID 36059797, 2022). "We further evaluated whether miR-299-3p decreased nasopharyngeal cancer cell proliferation and migration through modulating the MMP-2 gene expression." (PMID 36059797, 2022). "The MMP-2 production and cancer cell invasion in human nasopharyngeal carcinoma may be inhibited by salvianolic acid A via ERK signaling." (PMID 36059797, 2022). "Additional analysis revealed that overexpression of miR-299-3p inhibited the overexpression of MMP-2 in nasopharyngeal carcinoma cells whereas MMP-2 overexpression halts the miR-299-3p impact on the migratory and propagation inhibition of nasopharyngeal carcinoma cells." (PMID 36059797, 2022).
nasopharyngeal carcinoma (continued). "In nasopharyngeal carcinoma cells incubated with platelet-enriched plasma from exercising men, decreased MMP-2 and -9 activities, and increased platelet-nasopharyngeal carcinoma cell aggregation were measured when the subjects had exercised at high-intensity exercise (80%–100% VO2max)." (PMID 31936342, 2020). "In this context, the count of hybrid CTCs and the expression of MMP2 in these types of CTCs may play a significant role, which could be of great importance for guiding the treatment and monitoring disease progression in nasopharyngeal cancer." (PMID 40093514, 2025). "Therefore, miR-299-3p and MMP-2 could be important therapeutic targets for suppressing nasopharyngeal cancer growth and metastasis." (PMID 36059797, 2022). "In human nasopharyngeal carcinoma cells (NPC-39, HONE-1, NPC-BM), EGCG treatment significantly lowered the expression and activity of MMP-2 and reduced the motility and invasion potential of tumor cells by half." (PMID 39335164, 2024). "Nasopharyngeal carcinoma cells treated with PDT showed that IL-8, IL-1α, IL-1β, LC3BI, LC3BII, MMP2, and MMP9 levels were significantly higher than in groups that did not receive PDT." (PMID 37239013, 2023). "For example, VEGF enhances the expression of EMT markers N-cadherin, vimentin, and MMP2 and MMP9, reduces the expression of E-cadherin, promoting the invasion and migration of nasopharyngeal carcinoma cells." (PMID 35371324, 2022). "In nasopharyngeal carcinoma (NPC) cell lines, PRO has been shown to inhibit NE-induced MMP-2/9 and VEGF." (PMID 34790909, 2021). "Furthermore, AIMP2-DX2 promoted the proliferation, migration, and invasion of nasopharyngeal carcinoma (NPC) cells by upregulating MMP-2 and MMP-994." (PMID 32709848, 2020). "The upregulation of miR-124 has also been associated with reduced proliferation, migration, and invasion of nasopharyngeal carcinoma cells (C666-1 cells) via downregulation of STAT3, p-STAT3, G1/S-specific cyclin-D2 (CCND2) and Matrix Metalloproteinase-2 (MMP-2) expression in C666-1 cells." (PMID 36936170, 2023). "In nasopharyngeal carcinoma, RBMS3 activates caspase-9 and PARP to promote tumor cell apoptosis in a mitochondria-dependent manner, repressing the microvessels formation via downregulating MMP2 and β-catenin." (PMID 37968257, 2023). "Furthermore, matrix metalloproteinase 2 (MMP-2) expression was regulated by miR-299-3p, whereas MMP-2 knockdown significantly inhibited the capacity of nasopharyngeal cancer cells to form colonies and migrate." (PMID 36059797, 2022). "Tissue inhibitor of metalloproteinase-2 (TIMP2) is an upstream gene of MMP2, and the imbalance of MMP2/TIMP2 may have prognostic value for nasopharyngeal carcinoma." (PMID 32595725, 2020). "In nasopharyngeal carcinoma, DEPDC1 knockdown downregulated various downstream targets, such as c−Myc, BCL2, MMP2 and MMP9, which participated in proliferation, tumorigenesis, and metastasis, suggesting that DEPDC1 might be a vital factor in these biological processes." (PMID 36768316, 2023). "Moreover, this study showed that the positivity rate of MMP2 in CTCs was not related to the recurrence of nasopharyngeal cancer in patients, a finding that could be attributed to the insufficient sample size of this study." (PMID 40093514, 2025). "Conversely, overexpression of PGC1α induced MMP2 and CD44 expressions in non-metastatic nasopharyngeal carcinoma 6-10B cells." (PMID 27626695, 2016).
rheumatoid arthritis (43 papers, 2005 to 2025). A chronic, systemic autoimmune disorder characterized by inflammation in the synovial membranes and articular surfaces. "On the other hand, MMP2 is implicated in the association of rheumatoid arthritis to HCM and DCM." (PMID 36385157, 2022). "For example, MMP9 upregulation has been documented in rheumatoid arthritis, while increased MMP2/9 expression facilitates resolution of pulmonary inflammation and fibrosis in patients with COVID-19." (PMID 40646747, 2025). "A recent study showed that the MMP-2 enzyme is excessively secreted in the joints of patients with rheumatoid arthritis and plays an important role in inflammation and immunity." (PMID 35119317, 2022). "Once the Pro-Infliximab encounters the overexpressed MMP-2/9 and is specifically hydrolyzed in the disease region of rheumatoid arthritis (RA), the cleaved Pro-Infliximab is specifically activated and neutralizes the target antigen to suppress RA progression." (PMID 32586313, 2020). "Vitamin K-dependent protein C is an activator of several matrix metalloproteinases (MMPs), including MMP2, 9 and 13, and has shown to be significantly elevated in the synovium and synovial fluid of patients with rheumatoid arthritis (RA) and OA." (PMID 30822327, 2019). "Rheumatoid arthritis patients exhibiting higher serum FBG levels relative to healthy controls also demonstrated relatively reduced binding of serum MMP-2 to gelatin." (PMID 30867536, 2019). "The suppressive role of MMP-2 and a pivotal role of MMP-9 in the development of inflammatory joint disease was described in rheumatoid arthritis and other studies support this antagonistic role of MMP-2 and MMP-9 in inflammation." (PMID 28118356, 2017). "IL-1β increased the transcriptional and translational levels of MMP-1 and MMP-13 in rheumatoid arthritis FLSs, whereas the levels of MMP-2 and MMP-9 were unaffected." (PMID 17697361, 2007). "Moreover, Circ_0088194 stimulates the invasion and migration of fibroblast-like synovial cells in rheumatoid arthritis via the miR-766-3p/MMP2 axis." (PMID 38866992, 2024). "We tested whether mAlb-CTLA4Ig could be digested by MMP2/9 (type IV collagenase), which are highly upregulated in rheumatoid arthritis." (PMID 36797799, 2023). "Additionally, our previous study on rheumatoid arthritis also found that LOX expression levels in synovial fluid were positively correlated with the expression levels of MMP-2 and MMP-9." (PMID 31777578, 2019). "MMP-2 produced by synovial cells such as monocytes and macrophages may play a role in angiogenesis and the progression of rheumatoid arthritis." (PMID 30059520, 2018). "Notably, expression of both MMP-9 and MMP-2 is enhanced in the joints of patients with rheumatoid arthritis, while MMP-9 is overproduced in the osteoarthritic bone tissue." (PMID 29137306, 2017). "MIF also induces the rheumatoid arthritis synovial fibroblast MMP-2 expression." (PMID 24586879, 2014). "All MMP-9 and MMP-2 proteoforms were identified in archival synovial fluids with the use of zymography analysis and the levels of MMP-9 versus MMP-2 were studied in various arthritic diseases, including rheumatoid arthritis (RA)." (PMID 34912337, 2021). "For example, umbelliferone has been demonstrated in rheumatoid arthritis by diminishing the synthesis of proinflammatory factors, including MMP-9 and MMP-2, and by impeding the inflammatory response, invasion, and migration of fibroblast-like synovial cells." (PMID 40166460, 2025). "In vitro experiments have shown that the JBQG drug serum can inhibit the expression of cytokines (IL-6, IL-8, IL-22, IL-23), chemokine proteins and mRNA expression (MMP-1, MMP-2, MMP-3, MMP-9, MMP-13) in rheumatoid arthritis synovial fibroblasts (RA-FLS)." (PMID 37180723, 2023). "Circ_0088194 could promote rheumatoid arthritis fibroblast-like synoviocytes (RA-FLSs) invasion and migration via the miR-766-3P/Matrix Metalloproteinase 2 (MMP2) axis." (PMID 37298501, 2023).
rheumatoid arthritis (continued). "Rheumatoid arthritis (RA) is characterized by increases in MMP-2, MMP-3, and MMP-9." (PMID 36830637, 2023). "As in chondrocytes, EGCG can also suppress the IL-1β-induced MMP-2 and TNF-α-induced MMP-1 and 3 production in rheumatoid arthritis synovial fibroblasts." (PMID 33374730, 2020). "Another of our previous studies, on rheumatoid arthritis, found that inhibition of LOX expression in rat synovial fluid can downregulate MMP-2 and MMP-9 expression." (PMID 31777578, 2019). "Immunohistochemical staining of rheumatoid nodules has shown positive staining of epithelioid cells for HLA-DR, CD68, lysozyme, MMP-2, MMP-3, MMP-9 and Ki67." (PMID 19604347, 2009). "The expression of CD147 is upregulated in the rheumatoid arthritis synovial membrane and correlates with MMP-1, MMP-2, and MMP-3 upregulation." (PMID 16207318, 2005). "In patients with OA, the immunoexpression levels of TNF-α, IL-1β, IL-7, MMP-1, MMP-2, and MMP-3 were significantly higher in patients with active rheumatoid arthritis (RA), whereas the immunoexpression levels of IL-1, IL-2, IL-4, IL-6, IL-15, IL-18, and MMP-3 were not statistically different." (PMID 40004793, 2025). "For fibroblasts, transforming growth factor (TGF)-β1 or tumor necrosis factor (TNF)-α induction can enhance the expression of MMP2 and MMP9 in fibroblasts, while the endogenous MMP2 and MMP9 contribute to the survival and proliferation of rheumatoid arthritis (RA) synovial fibroblasts." (PMID 37653282, 2023). "Moreover, MMP-2 and MMP-9 are involved in inflammatory joint diseases, including rheumatoid arthritis, through degradation of cartilage and joint tissues." (PMID 38069361, 2023). "In a word, a MMP-2 enzyme-sensitive and precise RAW264.7 cell targeting nanoparticle containing Cel was successfully prepared, which had broad application prospects in the treatment of rheumatoid arthritis in the future." (PMID 35119317, 2022). "Further, MMP2 expression was observed in HCM and rheumatoid arthritis." (PMID 36385157, 2022). "CXCL12, C3, FN1, COL1A2, ACTB, VCAM1, and MMP2 were identified and finally verified as the hub genes, mainly enriched in pathways like leukocyte transendothelial migration, PI3K-Akt signaling pathway, viral myocarditis, rheumatoid arthritis, and platelet activation." (PMID 36398072, 2022). "Similarly, previous studies reported a strong correlation between the expression of VEGF and MMP-9, but not with MMP-2, in cancer patients, and in the synovial fluid of patients with rheumatoid arthritis." (PMID 24392031, 2013). "The inflammatory targets that mediate rheumatoid arthritis mainly include (TNF, PTPN11, IL6, etc.); the main targets that mediate RA oxidative stress are NOS3; the targets that mediate the destruction of extracellular matrix tissue in RA mainly include (MMP9, MMP2, ANXA5, etc.)." (PMID 38238321, 2024). "This is consistent with a previous report showing that CypA increased MMP9, but not MMP2, expression via CD147 in rheumatoid arthritis." (PMID 23031673, 2012).
COVID-19 (42 papers, 2020 to 2026). A disease caused by infection with severe acute respiratory syndrome coronavirus 2. "On the other hand, other studies found that MMP2 is associated with severe COVID-19 due to hyperinflammation and lung tissue damage caused by the decrease in collagen levels." (PMID 39965032, 2025). "It has been observed that high levels of ANG II in COVID-19 are associated with endothelial injury and that this peptide increases MMP-2 protein expression levels." (PMID 37372128, 2023). "In patients with severe COVID-19, both MMP-2 and MMP-9 levels in circulation were altered and associated with the risk of in-hospital death." (PMID 36482481, 2022). "Furthermore, COVID-19-associated lung damage has also been shown to be associated with MMPs, for instance, upregulation of gene expression of MMP2 and MMP9 in COVID-19 patients is associated with increased risk of respiratory failure." (PMID 39965032, 2025). "Interestingly, MMP-2 expression is linked to delayed graft function after kidney transplantation while cleavage of histones has been associated to reduced development of acute kidney injury in severe COVID-19 ICU patients." (PMID 36662718, 2023). "MMP-2, MMP-7, MMP-8, and neuropilin-1 were positively correlated, aligning with prior findings of elevated MMPs in severe COVID-19, linked to tissue damage and repair." (PMID 40557167, 2025). "The severe form of COVID-19 has many similar features to sepsis, and both MMP-2 and MMP-9 have been considered potential biomarkers for septic patients." (PMID 37509076, 2023). "Similar to MMP-2, MMP-3 is implicated in the onset of neurological damage in COVID-19 and is upregulated by the spike protein of SARS-CoV-2." (PMID 37372128, 2023). "Regarding zymography data, on the hospital admission of COVID-19 patients with a higher plasma activity, MMP-2 and MMP-9, compared to HD, were observed (p < 0.0001 and p < 0.0001, respectively) (respectively)." (PMID 37509076, 2023). "At first, we demonstrated that MMP-2, MMP-9, and TIMP-1 were elevated among COVID-19 patients and associated with COVID-19 severity, which is consistent with altered extracellular matrix remodelling." (PMID 37509076, 2023). "Elevated serum and cerebrospinal fluid (CSF) levels of MMP-2 enzymatic activity were identified in samples referring to individuals affected by COVID-19 with neurological sequelae." (PMID 37372128, 2023). "Severe cases of COVID-19 have sepsis-like features, with MMP-2 and -9 considered potential biomarkers for septic patients." (PMID 37372128, 2023). "Generally, decreased plasmatic levels of MMP-2 content in patients with COVID-19 represent a state of severe inflammation, similar to that seen in patients with sepsis." (PMID 37372128, 2023). "We also investigated the ratios MMP-2/-9 vs. NGF/BDNF/NFL because it was proposed as a novel method to predict COVID-19 morbidity and mortality." (PMID 36831321, 2023). "Some researchers observed a higher concentration of MMP-2, 3, and 9 in the blood of COVID-19 patients on admission to the hospital compared to healthy people." (PMID 36079011, 2022). "In clinical studies, plasma levels of MMP-2, MMP-3, and MMP-9 were associated with the severity of patients with COVID-19." (PMID 36142454, 2022). "MMP-2/MMP-8 activity is involved in the lung pathogenesis of patients with COVID-19 by increasing the influx of immune cells into the lungs, secreting HLA-G, and regulating the immune response through oxidative stress." (PMID 36142454, 2022). "Uncontrolled MMP-2-activity can be highly pro-inflammatory and affect lung physiology with severe COVID-19." (PMID 35625532, 2022). "The zymographic analysis of CSF samples from neuro-COVID-19 patients evidenced on the gel two main lysis bands, present at different levels, with an apparent molecular mass of 72 and 92 kDa, corresponding to MMP-2 and MMP-9, respectively." (PMID 36010557, 2022).